ABCC2 (ATP binding cassette subfamily C member 2)
Diseases named in the same sentence as ABCC2 in open-access papers (continued):
Sharing a sentence is not in itself a finding about the gene and the disease.
cancer (continued). "Our current study includes assessment of select ABC superfamily gene members (including ABCB1, ABCC1, ABCC2 and ABCG1) known to act as active drug transporters to reduce accumulation of chemotherapy drugs within resistant cancer cells." (PMID 30477242, 2018). "The major ABC superfamily transporters associated with multidrug resistance development were ABCB1, MRP2/ABCC2, and BCRP/ABCG2, which were often enriched with cells cancer stem cell-like phenotypes." (PMID 28903328, 2017). "ABCC2 transports LTB4 and probably other eicosanoids which are potent stimulators of inflammatory signalling pathways leading to inflammation and cancer." (PMID 25793771, 2015). "In addition to P-gp and MRP1, other ABC transporters such as MRP6 (ABCC6), MRP2 (ABCC2), MRP7 (ABCC10), and MRP3 (ABCC3) also contribute to the development of drug resistance in various cancers." (PMID 39679367, 2024). "Moreover, gene expression of some transporters (ABCC1, ABCC2, ABCC3, and ABCB3) was significantly elevated in recurrent cancer lesions compared with benign or malignant ovarian tissue." (PMID 35164068, 2022). "Finally, RT-PCR and WB showed that CDH17, IGF2BP1, IGFBP1, ABCC2, and HMGA2 were differently expressed between human lung fibroblast (HLF) cells and cancer cells." (PMID 35903696, 2022). "Additionally, we also observed an up-regulation in some cancer stem cell markers such as NANOG, ABCC2, ABCC5, CD44 and KLF450,51." (PMID 31597943, 2019). "Reports suggest that ABCC2 and other ABC transporters induce cancer resistance to TKIs." (PMID 29896907, 2018). "Comparing tumor and normal tissues, three of the five analyzed genes showed a significant lower expression in tumors than in healthy control tissues (ABCB1, p<0.0001; ABCC2, p<0.005; ABCG2, p<0.0001), whereas ABCC1 expression was significantly up-regulated in the carcinomas (p<0.0001)." (PMID 25275603, 2014). "Although multidrug resistance-associated protein 2 (MRP2/ABCC2) has been reported to transport DDP and confered resistance to DDP, actually the mechanisms of decreasing of DDP accumulation in resistant cancer cells have not been fully elucidated yet." (PMID 22304828, 2012). "It is suggested that no reduction in transporters other than ABCC2 may affect anti-cancer drug excretion in SC144-treated cells by inhibiting the gp130/STAT3 pathway." (PMID 35565185, 2022). "ABCA1, an ABC transporter, but not ABCB1, ABCC1 or ABCC2, might be involved in the anti-cancer drug resistance observed in DU145 cells stably overexpressing embigin." (PMID 30041429, 2018). "Although in our EVs from eribulin-treated cancer cells, ABCC11 mRNA was not up-regulated, we found that both ABCC2 (log2FC = +4.570, about 23 times more) and ABCG2 (log2FC = +2.366, about 5 times more) were up-regulated." (PMID 38534323, 2024).
tumor (66 papers, 2008 to 2026). "Notable associations include survival related to ABCB1 and ABCC2 variants, tumor occurrence linked to CYP2B6 rs3745274, and renal function affected by multiple pharmacogenes." (PMID 40761554, 2025). "Increased tumor risk correlated with ABCC2 variants in donors and decreased risk with CYP2B6 rs3745274 in recipients." (PMID 40761554, 2025). "Conversely, a significant (p-value: 0.043) association with an increased risk (OR: 13.09) of tumor appearance during the follow-up was found in patients receiving a kidney with the AA variant in ABCC2 rs2273697." (PMID 40761554, 2025). "An inverse association between ABCC2 expression in the tumor and chemotherapy response and/or disease prognosis has been established in clinical trials." (PMID 38612927, 2024). "These suggest that the impact mechanism of the ABCC2 rs717620 variant, situated on the promoter region, on tumours, resembles the influence of ABCC2 expression on tumorigenesis." (PMID 39095325, 2024). "Meanwhile, the ABCC1 SNP rs35628 was associated with the pathological characteristic of tumor size (p value = 0.014), while the ABCC2 SNP rs2273697 was significantly associated with estrogen receptor status (p value = 0.013)." (PMID 31391850, 2019). "In tumor cell lines, ABCC2 mRNA overexpression was associated with resistance to etoposide, vincristine, cisplatin, doxorubicin and epirubicin." (PMID 27988838, 2017). "Genotyping studies looking at single nucleotide polymorphisms (SNPs) have also revealed that specific variants of the ABCC2 gene were prognostic of tumor recurrence during tamoxifen monotherapy." (PMID 26883574, 2016). "Additionally, compared to ABCC2‐low PRCCs, ABCC2‐high PRCCs were significantly enriched with tumor‐associated macrophages (TAM), including M0 (p = 0.018), M1 (p < 0.001), and M2 (p = 0.021) phenotypes." (PMID 41259021, 2026). "The combination in donor of GG variant in ABCC2 rs2273697 with AG or AA variants in rs4244285 of CYP2C19 metabolizer gene could reduce the risk of tumor occurrence, with an OR < 0.2 in both cases." (PMID 40761554, 2025). "In this sense, GA variant in rs2279343 of recipient when coinciding with GG variant in ABCC2 rs2273697 of donor could increase the risk of tumor occurrence with a 5.3 odds ratio." (PMID 40761554, 2025). "So, what is the molecular basis underlying the tumour suppressive activity of ABCC2?" (PMID 39095325, 2024). "Thus, ABCC2 may induce an increased GSH synthesis to promote tumor progression, associated with nitrogen metabolism." (PMID 35903696, 2022). "Because rs717620 is located in the 5′UTR of the ABCC2 transcript, the −24C > T variant may increase ABCC2 expression, especially in tumor tissue; this may partly explain the resulting inhibition of drug resistance and improved responses and outcomes associated with this SNP." (PMID 27487151, 2016). "Overall, our findings suggest that ABCC2‐high PRCCs exhibit a tumor‐permissive milieu featuring increased CTL within a predominantly immunosuppressive microenvironment, driven by Treg and M2 TAM." (PMID 41259021, 2026). "Preclinical experiments confirm that targeting ferroptosis-related pathways (such as the USP7/SCD axis and ABCC2-mediated glutathione efflux) effectively inhibits tumor growth and metastasis." (PMID 40861444, 2025). "Specifically, in LUAD, ABCC2 expression was significantly elevated in tumor tissues compared to normal tissues, suggesting its potential involvement in LUAD pathogenesis and progression." (PMID 40429829, 2025). "ABCC2 and ABCG2 are two members of the ABC transporter family that have been widely identified in tumor cells and have been associated with response to therapy and disease prognosis." (PMID 38612927, 2024). "Several studies prove that overexpression of ABCC2 makes the tumour cell acquire multi‐drug resistance." (PMID 39095325, 2024).
tumor (continued). "The alteration of the tumour microenvironment resulting from glutathione efflux by ABCC2 is also worthy of further observation in subsequent studies." (PMID 39095325, 2024). "Meanwhile, we used patient‐derived tumour‐like cell clusters (PTCs) to model the clinical relevance of ABCC2 24C > T." (PMID 39095325, 2024). "Previously, ABCC2 was reported as an anion pump protein highly expressed in various tumours and promotes tumour drug resistance through the efflux of chemotherapeutic agents." (PMID 39095325, 2024). "ABCC2 up-regulation in tumor cells can make them resistant to CDDP, along with many other cytotoxic drugs." (PMID 35664698, 2022). "The present study identified ABCC2 gene expression to be significantly higher, four times, in CS tumour samples than NS." (PMID 32564237, 2020). "Most of these transporters, such as the multidrug resistance-associated protein-2 (MRP2, gene symbol ABCC2) are highly expressed in tumor cells." (PMID 28423714, 2017). "Of all the ABC transporters, ABCC2, also designated MRP2 or cMOAT, had been identified to confer cellular resistance of tumor cells to various anticancer drugs including cisplatin." (PMID 18834541, 2008). "Our in vivo model also confirmed that after treatment with cisplatin, the growth speed of tumor of the ABCC2-knockdown CNE2 cells was markedly slower compared to that of parent CNE2 cells and CNE2 cells with negative control construct." (PMID 18834541, 2008). "Additionally, ABCC2‐high PRCCs had higher PD‐L1 IHC positivity (combined positive score ≥ 1, p = 0.035; tumor proportion score ≥ 1%, p = 0.006) and immune predictive signature score (p = 0.029)." (PMID 41259021, 2026). "Additionally, we observed a reduction in activated dendritic cells in ABCC2‐high PRCCs, impairing antigen presentation and reducing tumor recognition." (PMID 41259021, 2026). "In the tumor microenvironment, stromal-derived MK from cancer-associated fibroblasts (CAFs) promotes cisplatin resistance by upregulating the lncRNA ANRIL, which induces the expression of multidrug-resistant proteins MRP1 and ABCC2." (PMID 39940704, 2025). "Furthermore, patient‐derived organoids and patient‐derived tumor‐like cell clusters were used to observe impact of ABCC2 on therapeutic effect." (PMID 39095325, 2024). "Third, additional studies on the effect of the ABCC2 rs2273697 and ERCC2 rs1799793 variants on protein expression in the tumor may contribute further evidence on the clinical utility of these variants as treatment predictors." (PMID 39771563, 2024). "In vivo, ABCC2 knockdown enhanced the cytotoxicity of DDP to subcutaneous A549 tumours." (PMID 32815556, 2021). "Besides, we verified the effect of SOX2-β-catenin/Beclin1/autophagy signaling-ABCC2 axis in tumor growth and chemoresistance in vivo via mouse models." (PMID 33953166, 2021). "Therefore, we found that the high expression of ABCC2 in various tumour cell lines is closely related to the resistance of these tumour cells to platinum drugs." (PMID 32815556, 2021). "Since we found that both ABCC2 rs1885301 and rs4148386 polymorphisms had the HWE departure in women, we investigated potential differences in the ABCC2 genotypes distribution between sexes by tumor side." (PMID 31395900, 2019). "Blockage of ABCC2 in addition to the standard first‐line therapies of metastatic RCCs might be of added benefit to the tumor treatment." (PMID 29896907, 2018). "ABCC2 is expressed in many tumor tissues, and tumor cells that overexpress ABCC2 might acquire multidrug resistance." (PMID 27487151, 2016). "And the impacts of the lower level of the expression of ABCC2 from the FRD might be beneficial to the growth of the tumor in FRD-LC rats." (PMID 26665149, 2015). "This immune profile may contribute to tumor progression and immune evasion in ABCC2‐high PRCCs." (PMID 41259021, 2026).
tumor (continued). "Additionally, the extensive amino acid starvation used to mimic metabolic stress in the tumour microenvironment suggests that ABCC2 could serve as a marker for overcoming GC resistance and is closely associated with amino acid metabolism." (PMID 39095325, 2024). "Moreover, ABCB1 and ABCC2 could play an overlapping function in elimination of hepatotoxicity of antitumor drugs, and in drug resistance of tumor cells to CP." (PMID 33240085, 2020). "ABCC2 expression is present in many tumor tissues and may lead to multidrug resistance." (PMID 27590272, 2016). "ANRIL knockdown in tumor cells depicted reduced apoptosis and proliferation and increased levels of cisplatin sensitivity by impairing drug transporters MPRP1 and ABCC2." (PMID 39940704, 2025). "In the xenograft model with high ABCC2 expression, we observed that constricting amino acid intake in conjunction with GPX4 inactivation resulted in notable tumor regression." (PMID 39095325, 2024). "Significant decreases in tumour sizes and masses were noted in the high ABCC2 expression groups treated with RSL3 compared to the ABCC2 knockout group (p < 0.001)." (PMID 39095325, 2024). "ABCC2 and GSH can co-transport efflux drugs to reduce drug accumulation and cytotoxicity in tumor cells." (PMID 35903696, 2022). "We analyzed for expression of five ABC transporters ABCB1, ABCC1, ABCC2, ABCC3 and ABCG2 using immunohistochemistry in 103 pre-treatment tumor specimens obtained from patients with CHL." (PMID 22871336, 2012). "Our results imply that perhaps such a regimen will result in greater cytotoxicity to tumor cells, yet it will make the remaining tumor cells more resistant to CDDP, probably mediated by ABCC2, and finally lead to poor prognosis." (PMID 20628484, 2010). "Conversely, the significant downregulation of MAP2K6, ABCC2, and MDGA suggests impaired MAPK signaling, which may affect tumor cell proliferation, differentiation, and drug resistance." (PMID 40061903, 2025). "What is most important is that these compounds only slightly influenced the expression of the ABCB1, ABCC1, and ABCC2 genes and the level of the MDR1 protein in the studied colon LS 174T and prostate DU 145 tumor cells, especially for the C-2028, C-2045, and C-2053 derivatives." (PMID 39683740, 2024). "Additionally, in the gastric xenograft mouse model characterized by high ABCC2 expression, we noted that restricting amino acid intake in combination with GPX4 inactivation led to significant tumour regression." (PMID 39095325, 2024). "Of note, the presence of drug transporters (e.g., P-glycoprotein (ABCB1), breast cancer resistance protein BCRP (ABCG2), multidrug resistance protein 2 (MRP2) (ABCC2), multidrug and toxin extrusion protein 1 (MATE1) (SLC47A1)) at the BTB also influences the delivery of nanoparticles to the tumor." (PMID 37049234, 2023). "However, the expression levels of ABCC1 and ABCC2 drug efflux transporters were very similar between the non-tumor-initiating subpopulation (CD44−CD133- and CD44−CD133+ Caco-2 cells) and the tumor-initiating subpopulation (CD44+CD133+ Caco-2 cells)." (PMID 35433695, 2022). "lncRNA ANRIL knockdown in tumor cells inhibits proliferation, induces apoptosis and increases cisplatin cytotoxicity in tumor cells via impairment of the drug transporters MRP1 and ABCC2, which can be restored by treatment with human MK in a caspase-3/BCL-2-dependent manner." (PMID 35204785, 2022). "Besides, ADORA2A-AS1 promoted the expression of transforming growth factor-beta receptor 1 (TGFBR1) and ATP binding cassette subfamily C member 2 (ABCC2) via sponging miR-665, thereby exerting a tumor-promoting activity." (PMID 35034552, 2022).
tumor (continued). "Quercetin has been also reported to modulate the activity of some members of the multidrug-resistance transporters family, such as P-gp, ABCC1, ABCC2, and ABCG2, and the activity of ecto-5′-nucleotidase (NT5E/CD73), a key regulator in some tumor processes such as invasion, migration, and metastasis." (PMID 33918012, 2021). "In our analysis of a clinical gene expression dataset, we showed that ABCC2 was the only one of 18 oxaliplatin transporter candidate genes with differential tumour expression between CRC patients who did or did not respond to oxaliplatin-based chemotherapy." (PMID 31500349, 2019). "In our analysis of a clinical gene expression dataset, ABCC2 was the only one of 18 oxaliplatin transporter candidate genes with differential tumour expression between CRC patients who did or did not respond to oxaliplatin-based chemotherapy." (PMID 31500349, 2019). "MRP2 (ABCC2) was overexpressed (1.5-fold) in the tumours of patients who did not respond (P < 0.0001 Bonferroni post-test following Two-Way ANOVA; Two-way ANOVA Factors: Tumour response, P = 0.0025; Gene, P < 0.0001; Interaction, P = 0014)." (PMID 30783141, 2019). "Taken together, these findings show that CAF-derived MK acts on tumour cells by paracrine action, increasing lncRNA ANRIL expression in tumour cells and thus promoting the up-regulation of ABC family proteins MRP1 and ABCC2, which ultimately results in tumour cell resistance to cisplatin." (PMID 29176691, 2017). "In J82 tumor, genes related to drug resistance were not changed, except ABCC2 (ATP-binding cassette, sub-family B, member 1), which was reduced by DOX." (PMID 22824624, 2012). "Interestingly, ABCC2 blockage alone by MK571 also affected the PRCC2 cell line growth both in vitro and in vivo, in keeping with emerging evidence suggesting that ABC transporters contribute to tumor growth in ways beyond drug efflux." (PMID 29896907, 2018). "Multidrug resistant protein 2 (MRP2, ABCC2) is a membrane efflux transporter widely distributed in normal (hepatic canalicular membrane, lung, kidney blood brain barrier and intestinal epithelium) and tumor tissues." (PMID 24250423, 2011). "Based on our immune transcriptomic profiling, we demonstrated that ABCC2‐high PRCCs were infiltrated by CTL; however, the higher proportions of immune inhibitory cells including Treg and M2 TAM could impair the functions of CTL and could promote tumor progression." (PMID 41259021, 2026). "There were no significant changes in expression between the tumor and control tissues in the ABCB4, ABCA13, ABCC2, ABCC3, and ABCG2 genes." (PMID 36674773, 2023). "Furthermore, lncRNA ANRIL knockdown in tumour cells inhibited proliferation, induced apoptosis and increased cisplatin cytotoxicity of the tumour cells via impairment of the drug transporters MRP1 and ABCC2, which could be restored by treatment with human MK in a caspase-3/BCL-2-dependent manner." (PMID 29176691, 2017). "Interestingly, other ABC transporter genes that have been described to confer resistance in cell lines with acquired doxorubicin (e.g., ABCC1, ABCC2, and ABCG2) were not related to inherent anthracycline resistance in this panel of tumor cell lines." (PMID 40723843, 2025).
infection (4 papers, 2021 to 2025). The state of being infected such as from the introduction of a foreign agent such as serum, vaccine, antigenic substance or organism. "For instance, patient PKTx2’s heterozygosity for ABCB1 and ABCC2 variants, associated with tacrolimus metabolism and acute cellular rejection, likely contributed to the patient’s post-transplantation infection complications." (PMID 40126245, 2025).
adenocarcinoma (2 papers, 2016 to 2017). A common cancer characterized by the presence of malignant glandular cells. "Furthermore, we found that the ABCC2 rs717620 polymorphism increased the sensitivity to platinum in patients diagnosed with adenocarcinoma, smoker patients, and male patients." (PMID 27590272, 2016). "Relative mRNA expression of ABCC1 and ABCC2 drug transporters of cisplatin treatment of 3D co-culture aggregates of adenocarcinoma cell line A549-NHLF (A) and (B); 3D co-culture aggregates of squamous cell line H520-NHLF (C) and (D)." (PMID 28340578, 2017).
bacterial infection (2 papers, 2019 to 2021). "To investigate how bacterial infection impacts placental efflux transport potential, we investigated the expression of the of Abca1, Abcb1a, Abcb1b, Abcb4, Abcc2, Abcc5, Abcf2, Abcg1 and Abcg2 mRNAs in the mouse placenta at GD15.5 or GD18.5 following LPS challenge (4 h)." (PMID 34394055, 2021).